PKD1 (polycystin 1, transient receptor potential channel interacting)
Diseases named in the same sentence as PKD1 in open-access papers (continued):
Sharing a sentence is not in itself a finding about the gene and the disease.
breast cancer (continued). "Thus, our finding of increased Pkd1 levels in the mammary glands of corn oil-fed fathers’ offspring, compared with female offspring of lard-fed fathers, is in line with their lowest susceptibility to breast cancer." (PMID 27456846, 2016). "Interestingly, mammalian PKD1 is associated with the F-actin binding proteins cortactin and paxillin in invasive breast cancer cells where it may regulate cell adhesion and motility." (PMID 17592635, 2007). "In breast cancer cells, depletion of PKD1 stimulated migration in MCF-7 cells; however, the effect was higher when PKD2 was silenced." (PMID 37293129, 2023). "Rather, it would explain other studies showing that PKD1 negatively controls invasion by downregulating MMP9 expression in breast cancer cells." (PMID 37293129, 2023). "In principle, these data contradict previous findings suggesting PKD1 as an EMT repressor in breast cancer [reviewed in detail in]." (PMID 37293129, 2023). "For example, while PKD1 has tumor promoting functions in pancreatic cancer, it shows tumor suppressive functions in breast cancer." (PMID 37293129, 2023). "The pro-growth/survival effects of PKD1 on breast cancer cells are specifically mediated through activating a MEK/ERK-dependent signaling pathway and are totally independent of the PI3K/AKT cascade." (PMID 35805075, 2022). "Similar to a previous study in breast cancer cells, PKD1 knockdown significantly compromised the frequency of repopulation of the cancer stem-like cells, when compared with the control pNET cells." (PMID 36497140, 2022). "Previous studies have shown that PKD1 promoted breast cancer cell proliferation and estrogen independence." (PMID 35816294, 2022). "PKD1 overexpression promotes breast cancer cell proliferation through accelerating G0/G1 to S phase transition in the cell cycle." (PMID 35805075, 2022). "In breast cancer cell lines, overexpression of constitutively active PKD1 repressed tumor cell migration, whereas downregulating PKD1 led to increased cell migration." (PMID 33807058, 2021). "It was reported that PKD1 inhibited breast cancer cell invasion by negatively regulating the transcription of several MMPs, including MMP-2, MMP-7, MMP-9, MMP-10, MMP-11, MMP-13, MMP-14, and MMP-15." (PMID 33807058, 2021). "In prostate and breast cancer cells, PKD1 phosphorylated Snail, resulting in the nuclear export and proteasomal degradation of Snail and subsequent inhibition of EMT." (PMID 33807058, 2021). "Supporting our observations that PKD localizes to the actin belt, PKD1 has been observed in invasive MDA-MB-231 breast cancer cells localized to invadopodia, actin-rich structures closely related to the podosomes that make up the actin belt." (PMID 32033440, 2020). "By defining PKD1 as a functional target of BPA in breast cancer cell proliferation and tumor development, they provide new insights into the pathogenesis related to the exposure to BPA and other endocrine disruptors acting similarly." (PMID 32082170, 2019). "Recent studies demonstrated that there is a correlation between the expression of PKD1 and ERα in breast cancer cells." (PMID 30619291, 2018). "Our data indicate that PKD1 in breast cancer cells indeed is the main regulator of PIP5K1C phosphorylation at S448, but not at S650 (control)." (PMID 30555634, 2018). "We have previously shown that the Protein Kinase D1 (PKD1) can promote both proliferation and estrogen independence in breast cancer cells." (PMID 29796183, 2018). "It has been previously shown that PKD1 is down-regulated in breast cancer as compared to normal breast tissue." (PMID 29796183, 2018). "Overexpression of constitutively-active PKD1 inhibits the invasion of breast tumor cells, while knockdown of PKD1 confers invasiveness to non-invasive breast cancer cells, an effect that is potentially mediated through negative regulation of MMP expression." (PMID 30419840, 2018).
breast cancer (continued). "We showed that among the three members of the PKD family, only PKD1 is an independent prognostic factor in our entire breast cancer cohort." (PMID 29796183, 2018). "Pharmacological inhibition or siRNA-mediated depletion of PKD1 has previously shown cytotoxicity in melanoma, breast cancer, prostate cancer and pancreatic cancer cells." (PMID 29796183, 2018). "Previous in vitro and in vivo work indicated that PKD1, if expressed in breast cancer, prevents cell migration and invasion at multiple levels." (PMID 30555634, 2018). "In a previous work, we have shown that PKD1 overexpression confers estrogen independence in MCF7 breast cancer cells." (PMID 29796183, 2018). "The biological role of PKD1 in breast cancer is still unclear but we have previously demonstrated that it can drive estrogen independence in ER+ BC cells." (PMID 29796183, 2018). "The Wasf2 complex regulates lamellipodia formation and is under regulation of PKD1-mediated pathways in the pancreas and breast cancer cells." (PMID 29258556, 2017). "We show that lysophosphatidic acid/protein kinase D1 (LPA/PKD-1)-CD36 signaling is a bona fide breast cancer promoter via stimulating microvascular remodeling in chronic diet-induced obesity (DIO)." (PMID 28186980, 2017). "For example, PKD1 expression has been shown to block breast cancer cell migration and invasion in vitro and in vivo and to block matrix-metalloproteinase (MMP) expression." (PMID 28842658, 2017). "In a cohort of invasive human breast cancer samples, over 95% of samples had reduced expression of PKD1 when compared to normal breast tissues." (PMID 26848698, 2016). "PKD1 also reduced serum- and anchorage-dependence for proliferation and survival in vitro and drove tumorigenesis in xenograft models of mammary tumors." (PMID 27042159, 2016). "In this study, we highlight the role of the serine/threonine-protein kinase D1 (PKD1) in ERα-positive breast cancers." (PMID 25287328, 2014). "Growth of ERα-positive MCF-7 and MDA-MB-415 human breast cancer cells was assayed in adherent or anchorage-independent conditions in cells overexpressing or depleted for PKD1." (PMID 25287328, 2014). "This newly described property of PKD1 to confer independence to estrogens is of major importance since independence to these hormones characterizes more aggressive breast cancers which are unresponsive to antiestrogen therapy." (PMID 25287328, 2014). "In fact, the invasiveness of breast cancer cells correlates with the formation of a ternary complex between PKD1, cortactin and paxillin in invadopodia-enriched membranes." (PMID 25287328, 2014). "These anti-proliferative results are consistent with the findings in prostate and breast cancer, wherein the overexpression or activation of PKD1 suppressed cancerous phenotype of the cells." (PMID 25149539, 2014). "As a strong correlation between PKD1 expression and invasiveness was observed in PKD1-positive breast cancer cells, the role of PKD1 in the invasiveness of ERα-positive breast cancer cells was analysed." (PMID 25287328, 2014). "In breast cancer, epigenetic silencing of PRKD1 gene promoter has been reported to directly correlate with the loss of PKD1 expression and the invasive potential of breast tumors or cells." (PMID 25149539, 2014). "Four of the eight PKD1-positive breast cancer cell lines (50%) expressed high levels of ERα as compared to five of the 30 PKD1-negative breast cell lines (16.6%)." (PMID 25287328, 2014). "PKD1 is a kinase that negatively affects directed cell migration and invasion of tumor cells and maintains the epithelial phenotype of breast cancer cells through negative regulation of EMT." (PMID 23971832, 2013). "The re-expression of active PKD1 in highly invasive breast cancer cells blocks cell invasion and the reduction of PKD1 expression in very low-invasive breast cancer cells increases the invasive ability of these cells." (PMID 19243594, 2009).
breast cancer (continued). "To test this we utilised the very low-invasive breast cancer cell line MCF-7 which we have shown moderately expresses PKD1." (PMID 19243594, 2009). "Here we show that PKD1 expression is decreased in invasive breast cancer tissue and that PKD1 expression is silenced in invasive breast cancer cell lines." (PMID 19243594, 2009). "Non-invasive or very low-invasive breast cancer cell lines such as BT-474 or MCF-7 and the normal breast cancer cell line MCF-10A moderately expressed PKD1." (PMID 19243594, 2009). "We further utilised specific PKD1-shRNA and a system to inducibly-express PKD1 to analyse the role of PKD1 in the invasive behaviour of breast cancer cell lines in two-dimensional (2D) and three-dimensional (3D) culture." (PMID 19243594, 2009). "This knowledge can be applied to develop new therapeutic avenues such as the re-expression of PKD1 as one potential strategy to ameliorate breast cancer metastasis." (PMID 19243594, 2009). "Our data further suggest that PKD1 inhibits breast cancer cell invasion by regulating the expression of factors involved in the degradation of ECM." (PMID 19243594, 2009). "Nevertheless, these data further support the role of PKD1 as a tumor suppressor in breast cancer." (PMID 37293129, 2023). "In line with this, Lu and collegues concluded that inhibition of bromodomain-containing protein 4 (BRD4) in TNBC cell lines regulates SNAI1 in a PKD1-dependent manner, resulting in decreased migration and invasion in breast cancer cells and reduced tumor growth and metastasis in xenograft models." (PMID 37293129, 2023). "PKD1 is a key regulator of the stemness of breast cancer stem cells (BCSCs)." (PMID 35805075, 2022). "Additionally, PKD1 promoted αvβ3 integrin recycling through phosphorylating rabaptin-5 and inhibited both breast cancer and colorectal cancer cell invasion into fibronectin-rich matrices." (PMID 33807058, 2021). "PKD1 levels are significantly downregulated in breast cancer, acting as an antioncogene." (PMID 34249722, 2021). "Both PKD2 and PKD3 were preferentially expressed in breast cancer compared to PKD1." (PMID 30652415, 2019). "Moreover, we showed that increasing PKD1 expression levels significantly sensitized breast cancer cells to BPA-induced in vivo tumor growth." (PMID 32082170, 2019). "Moreover, we identified PKD1 as a poor prognostic factor in the whole breast cancer population and in the triple-negative breast cancer (TNBC) subtype specifically." (PMID 32082170, 2019). "Moreover, we demonstrated that PKD1 expression levels affect breast cancer cell proliferation in vitro and in vivo." (PMID 32082170, 2019). "Overall, since PKD1 is a negative regulator of cell migration and invasion in breast cancer, the phosphorylation status of this residue may serve as an indicator of aggressiveness of breast tumors." (PMID 30555634, 2018). "In the present study, our goal was to determine whether PKD1 is a prognostic factor and/or a relevant therapeutic target in breast cancer." (PMID 29796183, 2018). "The objective of the present study was to determine whether PKD1 can be a prognostic factor and/or a therapeutic target in breast cancer." (PMID 29796183, 2018). "This prompted us to determine whether PKD1 could be a potential prognostic factor and/or a therapeutic target in breast cancer." (PMID 29796183, 2018). "Moreover, PKD1 expression levels/activity and PIP5K1C phosphorylation at S448 are functionally linked in breast cancer, as shown by analyses of orthotopically-implanted tumors in an animal model." (PMID 30555634, 2018). "In addition, we have previously demonstrated that PKD1 can confer resistance to antiestrogen therapy in ERα+ breast cancer cells." (PMID 29796183, 2018). "Thus, our study defines PKD1 as a novel attractive prognostic factor and a potential therapeutic target in breast cancer." (PMID 25287328, 2014).
breast cancer (continued). "The overexpression of PKD1 in breast cancer cells inhibited multiple metalloproteinases, suppressed cellular motility, prevented epithelial to mesenchymal transition and modulated the tumor microenvironment leading to the suppression of tumor growth/progression." (PMID 25149539, 2014). "This interesting point suggests that PKD1 may also represent a novel attractive independent prognostic factor in breast cancer as recently described for esophageal squamous and laryngeal cancers." (PMID 25287328, 2014). "Moreover, overexpression of EGFR and HER2, whose ligand (i.e. the epidermal growth factor) is capable of inducing PKD1 activity, was observed in antiestrogen-resistant breast cancers." (PMID 25287328, 2014). "In conclusion, our study indicates that PKD1 expression might be critical, on the one hand, to the initiation of ERα-positive breast cancers and, on the other hand, to the progression to a more advanced tumour." (PMID 25287328, 2014). "Now, we know the status of PKD1 in a wide range of breast cancer cell lines." (PMID 25287328, 2014). "Interestingly, we observed that ERα-positive MDA-MB-415 breast cancer cells, that express high endogenous PKD1 levels, are also able to proliferate and survive in estrogen-free medium." (PMID 25287328, 2014). "PKD1 has also been attributed to possess a tumor suppressor function in breast cancer." (PMID 25149539, 2014). "However, a recent study by Borges and colleagues showed that re-expression of PKD1 reduces the invasive potential of the PKD1-negative MDA-MB-231 breast cancer cells." (PMID 25287328, 2014). "Since PKD1 overexpression confers resistance to antioestrogen ICI 182,780 in MCF-7 ERα-positive breast cancer cells, we investigated the possible relationship between PKD1 expression level and patient responsiveness to the most common antiestrogen agent in clinical use, i.e. tamoxifen." (PMID 25287328, 2014). "However, in invasive and high PKD1-expressing MDA-MB-415 cells, PKD1 knockdown strongly inhibited 17β-estradiol-induced and -independent invasion which further confirms the estrogen-dependent and -independent role of PKD1 in breast cancer progression." (PMID 25287328, 2014). "By comparing normal and tumor patient tissue as well as normal, noninvasive, and highly invasive breast cancer cell lines, we show that PRKD1 gene promoter methylation directly correlates with the loss of PKD1 expression and the invasive potential of breast tumors or cells." (PMID 23971832, 2013). "Furthermore, the expression and activity of PKD1 regulate the invasiveness of breast cancer cell lines by inhibiting the expression of multiple matrix metalloproteinases (MMPs)." (PMID 23971832, 2013). "In breast cancer, PKD1 may be a key protein that inhibits the invasive phenotype, since a knockdown of PKD1 expression by reverse genetics has been shown to increase the invasiveness of the non- or minimally motile MCF-7 cells." (PMID 23971832, 2013). "Since PKD1 was previously characterized as a negative regulator of cell motility, our data suggest that a PKD1 reexpression strategy may be used as a therapeutic approach to reduce or prevent breast cancer cell metastasis." (PMID 23971832, 2013). "So far, the only mutation in the PRKD1 gene found for breast cancer does not explain the loss of its expression, and it is conceivable that downregulation of PKD1 expression is due to epigenetic modifications such as DNA methylation of its promoter." (PMID 23971832, 2013). "This suggests that in breast cancer PKD1 is a molecular switch that regulates motility and its effects on E-cadherin expression and EMT may be one of the mechanisms it uses." (PMID 22276203, 2012). "To date, there was little known on the expression and function of PKD1 in breast cancer." (PMID 19243594, 2009). "Our findings show that PKD1 inhibits breast tumour cell invasion and thus may influence tumour cell dissemination and metastasis, the most lethal aspect of breast cancer." (PMID 19243594, 2009).
breast cancer (continued). "Moreover, by analysing PKD1 expression in the 1-HMT-3522 breast cancer cell progression model, we found that the T4/2 clone which shows increased invasiveness as compared with the S1 clone also expressed less PKD1." (PMID 19243594, 2009). "We next determined the PKD1 expression status in a subset of breast cancer cell lines." (PMID 19243594, 2009). "Therefore, PKD1 mediates breast cancer cell invasion through regulation of the expression of invasion-relevant MMPs." (PMID 19243594, 2009). "However, it has also been reported that phosphorylation of SNAI1 is not a prerequisite for its degradation, so the described mechanism may be unique to PKD1-positive breast cancer." (PMID 37293129, 2023). "Therefore, we asked whether BPA may specifically modulate the proliferation of four breast cancer cell lines that differently express ERα and PKD1." (PMID 32082170, 2019). "Thus, PKD1 is likely to be a relevant therapeutic target in breast cancer." (PMID 29796183, 2018). "In addition, although the phosphorylation of EVL-1 by PKD1 has been shown to occur in lamellipodia, filopodia and at cell-cell contacts, so far no information exists if it is predictive for aggressiveness of human breast cancer." (PMID 26336132, 2015). "Therefore, based on our current large-scale analysis, realized in 152 malignant breast tissues and in 38 non-cancerous and cancerous breast cell lines, and by using a more sensitive and specific method (qRT-PCR), we currently present PKD1 as a new pertinent marker for breast cancer invasion." (PMID 25287328, 2014). "Therefore, we suggest that PKD1 may become a new potential therapeutic target for initiated and advanced breast cancer treatment that may counteract endocrine therapy-resistance." (PMID 25287328, 2014). "Therefore, taken all together, these results suggest that PKD1 may represent a novel attractive prognostic factor for hormone responsiveness and metastasis in ERα-positive breast cancer." (PMID 25287328, 2014). "To date, in breast cancer, the role of PKD1 remains unclear." (PMID 25287328, 2014). "Since MCF-7 cells are estrogen-dependent and non-tumorigenic unless exogenous estrogen is provided to the mice, we determined in the present study whether PKD1 regulates cell sensitivity and/or dependence to estrogens in two different ERα-positive breast cancer cell lines." (PMID 25287328, 2014). "However, it is possible that PKD1 in this subtype of breast cancer may be regulated in its kinase activity." (PMID 23971832, 2013). "However, these mutations do not explain the loss of PKD1 expression during the invasive progression of breast cancer, suggesting another type of regulation." (PMID 23971832, 2013). "Moreover, targeted upregulation of PKD1 expression may be used as a therapeutic approach to reverse the invasive phenotype of breast cancer cells." (PMID 23971832, 2013). "Compared to PKD1, PKD2 and PKD3 were expressed at higher levels in the invasive breast cancer cell lines through analyzing the gene expression data from Cancer Cell Line Encyclopedia project and NCI60 Cell Line project." (PMID 30652415, 2019). "Compared to consistent tumor‐suppressive functions of PKD1 in breast cancer, how PKD2/3 functions in breast cancer are not fully understood." (PMID 30652415, 2019). "To confirm the role of this kinase in ERα-positive breast cancer, we have chosen to test the effect of its down-regulation in MDA-MB-415 cell line which is ERα-positive, expresses high levels of PKD1 and is invasive." (PMID 25287328, 2014). "On the other hand, 25.8% (8/31) of the breast cancer cell lines (BT474, HCC-202, Hs 578T, MCF-7, MDA-MB-134 VI, MDA-MB-415, MDA-MB-436 and PMC42) expressed marked PKD1 mRNA levels." (PMID 25287328, 2014). "Non-invasive or very low-invasive breast cancer cell lines such as BT-474 and MCF-7 and a normal breast cell line MCF-10A showed moderate PKD1 expression." (PMID 19243594, 2009).